BMP2 (bone morphogenetic protein 2)
Diseases named in the same sentence as BMP2 in open-access papers (continued):
Sharing a sentence is not in itself a finding about the gene and the disease.
cancer (continued). "Interestingly, expression of BMP2 is suppressed in wild type and unknown IDH status cancers, but high in some mutant samples in this data set." (PMID 28768481, 2017). "Interestingly, we found that TGF-β1, TGF-β2 and TGF-β3 mRNAs were all remarkably up-regulated in the co-cultured cancer cells and NFs using real-time PCR, whereas IL-4, IL-13, BMP2 and PDGF-bb mRNAs were not affected in these cells." (PMID 26857387, 2016). "Additionally, interrogation of publically available gene expression datasets revealed significant downregulation of BMP2 in metastatic recurrent compared to non-metastatic cancer (p = 0.02)." (PMID 27708551, 2016). "Moreover, we demonstrated a significant difference in BMP-2 expression between infiltrating carcinomas with (2.4 ± 0.1) or without microcalcifications (0.7 ± 0.1)." (PMID 24758513, 2014). "However, analysis in vitro may not represent the full biological effects of IL6 and BMP2 in vivo, as any interaction between them to promote cancer will be more complex in vivo." (PMID 38468450, 2024). "As expected, transwell migration of MCF-7 cells was changed very little by BMP-2 when they are cultured alone, but significantly increased when osteogenic cells are co-cultured —supporting that osteogenic cells and MBT may drive relocation of cancer cells toward sites releasing osteogenic signals." (PMID 32964116, 2020). "In contrast to previous studies in cancer and pituitary gonadotrope cells, our study in trophoblast cells is the first to implicate ALK2 in BMP2-induced non-canonical SMAD2/3 signaling." (PMID 29416020, 2018). "We determined that gremlin-1 strongly bound BMP-2 and BMP-4 but this binding did not affect its interaction with cancer cells." (PMID 22514712, 2012). "The GREM1Mut, which we clearly demonstrated, does not bind to BMP2 in both HCT116 and C2C12 cells may be a valuable reagent to further refine our understanding of GREM1-RTK signaling in cancer and other diseases." (PMID 41033552, 2025).
infection (56 papers, 2009 to 2026). The state of being infected such as from the introduction of a foreign agent such as serum, vaccine, antigenic substance or organism. "Our data indicate that loss of Bmp2 upon infection drives the increased expression of Rspo3, which expands from the stroma around the base to that higher up along the gland axis." (PMID 35332152, 2022). "Since we noticed that H. pylori already induced Bmp2 loss after two weeks of infection, we investigated to what extent T cells are found in the mucosa." (PMID 35332152, 2022). "This somewhat correlates with clinical findings since high doses of BMP-2 was also associated with a reduced infection rate following Type III open tibia fractures, potentially because of its ability to augment vascular supply to the injured area." (PMID 24101902, 2013). "In addition, we find that BMP2 inhibits Rspo3 expression in stromal cells, indicating that the loss of Bmp2 expression upon infection is responsible for the increased expression of Rspo3." (PMID 35332152, 2022). "Emerging approaches, including nitric oxide-releasing coatings and controlled BMP-2 delivery, offer promising solutions to complications such as infection and ectopic ossification." (PMID 41968945, 2026). "Apart from anti-infection, other biofunctions such as promoting bone healing and bone growth can be targeted by loading nPDA with molecules such as bone morphogenetic protein 2 (BMP2), adenosine, osteogenic peptides, and simvastatin." (PMID 37111718, 2023). "A similar trend was exhibited by INHBA and BMP2 - genes induced by infection in our bulk RNA-seq results previously shown to be YAP-responsive." (PMID 36923592, 2023). "Such conditions provide transduction of about 85% of viable cells with Ad-GFP after 3 days and lead to an increase in BMP2 gene expression and BMP-2 protein production within a week after infection with Ad-BMP2." (PMID 37443796, 2023). "The results revealed a significant increase in miR-664a-3p and Bmp2 expression after infection with the corresponding virus." (PMID 36246570, 2022). "In the stomachs of patients infected with Helicobacter pylori, it was observed that the inflammatory infiltrate induced by the infection produced BMP2, which was related to the increase of this protein in the organ." (PMID 33561140, 2021). "The infection induced increased intestinal IFNγ and BMP2 production during the acute phase as well as an increase in the inflammatory infiltrate." (PMID 33561140, 2021). "Briefly, we propose that, during the acute phase of infection, the increase in BMP2 is related to 1) the increase in inflammatory cells producing BMP2, 2) the maintenance of the intestinal proinflammatory profile, and 3) neuronal destruction." (PMID 33561140, 2021). "In the acute phase of infection, a significant increase in BMP2 production was observed compared to the control (p = 0.0303)." (PMID 33561140, 2021). "Our results demonstrate that infection induces the production of BMP2 differently in acute and chronic infections." (PMID 33561140, 2021). "Upon infection of foetal pericytes, ZIKV has been shown to interfere with the BMP2-SMAD pathway which is usually associated with physiological bone formation." (PMID 34658789, 2021). "Infection of foetal pericytes with Asian ZIKV led to increased levels of BMP2 in the supernatant, increased expression of key osteogenic genes such as RUNX2, and calcification." (PMID 34658789, 2021). "A significant intestinal BMP2 increase was observed at 30 days of infection, and this was closely related to the intestinal IFNγ increment and neuronal loss." (PMID 33561140, 2021). "After continued clinical use, the adverse effects of BMP-2 (e.g., inflammatory, ectopic bone formation, infection, and potential tumorigenicity) have come into focus; the high dose and off-label application of BMP-2 have also aroused concern." (PMID 34869325, 2021).
infection (continued). "Infection with both Ad-BMP-2 and Ad5-PDGF-BB virus resulted in production of mature BMP-2 and PDGF-BB mRNA and protein expressions." (PMID 33331538, 2020). "A few cytokines and chemokines of importance for tissue repair was also resistant to cleavage, including EGF, PDGF-B, BMP-2 and 14, indicating that these are stabilized to resist degradation to enable repair of damaged tissues after an inflammation/infection." (PMID 31963828, 2020). "Collectively, these results demonstrate that BMP-2–loaded lysostaphin-delivering hydrogels eliminate infection and drive defect repair, leading to functional bone regeneration." (PMID 31114804, 2019). "Next, the MSCs either with adeno-Lhx8, GI-Gal4DBD, LOV-VP16, and BMP2-shLhx8 infection or corresponding controls were loaded into the PLGA scaffolds." (PMID 31754390, 2019). "Follow-up studies should consider placing bacteria at the defect site before placing the hydrogel construct, as well as treating established bone defect infections with lysostaphin/BMP-2–loaded hydrogels in a subsequent surgery." (PMID 31114804, 2019). "We showed that BMP-2–loaded lysostaphin-delivering hydrogels eradicate infection and regenerate bone with similar mechanical properties to those of intact mouse radii." (PMID 31114804, 2019). "We also included a group of infection-only hydrogels containing 100 ng of BMP-2 that were dipped in gentamicin (10 mg/ml) to simulate the current therapeutic standard of locally delivered antibiotic-doped implants." (PMID 31114804, 2019). "The results show significantly increased mechanical properties for both infections treated with lysostaphin/BMP-2–delivering hydrogel and the sterile control group." (PMID 31114804, 2019). "Together, these results show that BMP-2–loaded lysostaphin-delivering hydrogels significantly improve bone regeneration compared to untreated infections and regenerate equal amounts of bone as sterile implants." (PMID 31114804, 2019). "We engineered a synthetic hydrogel that both induces bone regeneration and eliminates infection through the co-delivery of BMP-2 and lysostaphin, respectively." (PMID 31114804, 2019). "Clinical studies such as the BESTT study (BMP-2 Evaluation in Surgery and Tibial Trauma) have presented both an accelerated healing process and a lower infection rate after treatment with rhBMP-2." (PMID 30049273, 2018). "Infection of IFT80f/f and IFT80d/d OPCs with Ad-BMP2 or Ad-Runx2 significantly promoted BMP2 or Runx2 expression." (PMID 26996322, 2016). "In the MSC group, BMP-2 expression increased after the multiplicity of infection (MOI) was doubled from 500 to 1,000 PFU/cell." (PMID 25924919, 2015). "While, Ad-Cre infection significantly inhibited the Icariin-induced expression of BMP2, BMP4, ALP, and OC, Ad-Cre-mediated deletion of the β-catenin gene was demonstrated by the reduction of β-catenin mRNA and protein expression in these cells." (PMID 24348713, 2013). "Interestingly, in vitro infection of human fetal pericytes with Asian strain of Zika virus led to dedifferentiation of pericytes into bone forming cells via upregulation of bone morphogenetic protein 2 (BMP2)." (PMID 35309892, 2022). "We wondered whether the inhibition of Bmp2 expression upon infection also depends on a functional T4SS." (PMID 35332152, 2022). "As we had observed inhibition of Bmp2 expression in stromal cells upon infection, we now asked whether this, too, was induced by IFN-γ." (PMID 35332152, 2022). "In addition, Bmp2 expression was significantly downregulated after infection with the miR-664a-3p overexpression lentivirus." (PMID 36246570, 2022). "This study aimed to investigate BMP2 intestinal production in C57Bl/6 mice infected with the Y strain of T. cruzi as well as to correlate this production with parameters related to the immunopathogenesis of the experimental infection." (PMID 33561140, 2021).
infection (continued). "The inflammatory infiltrate was observed to be of greater intensity in the acute phase (moderate) than in the chronic phase (mild), which may be related to the fact that increased BMP2 levels were only observed at the beginning of the infection." (PMID 33561140, 2021). "BMP-2 enlarged the cultured cartilage after 5 days, while LV-shCdc5l infection negated this effect." (PMID 34298017, 2021). "Moreover, we found that BMP2 effectively upregulated Smad7 expression at 3 and 5 days after infection." (PMID 33588941, 2021). "Indeed, Bmp2 and Runx2 synergistically induced Smoc1 and Smoc2 expressions as an early response to infection." (PMID 34667264, 2021). "As the first report of BMP2 alteration after infection by T. cruzi, we suggest that this imbalance is not only related to neuronal damage but may also represent a new route for maintaining the intestinal proinflammatory profile during the acute phase." (PMID 33561140, 2021). "However, it is also plausible that, by inhibiting intestinal remodeling in the early stages of experimental infection, BMP2 plays a dual role." (PMID 33561140, 2021). "Based on this information, we speculate that, at the beginning of the infection, the increase in BMP2 is related to the inhibition of intestinal remodeling in our model." (PMID 33561140, 2021). "Since we observed, in the acute phase of the infection, significant BMP2, and IFNγ increases, we asked if IFNγ production could be correlated with the BMP2 increase." (PMID 33561140, 2021). "In addition to the correlation involving IFNγ, a moderate, negative, and significant correlation was observed between the BMP2 level and the number of myenteric plexus neuron cells but only during the acute phase of the experimental infection." (PMID 33561140, 2021). "In addition, the overexpression of Cuecd2 using Ad-CUEDC2 infection significantly inhibited BMP2-induced ALP activity and mineralized nodule formation." (PMID 32393737, 2020). "We examined the expression of hallmarks of BMP signaling during mycobacterial infection and found transcript levels of Bmp2, Bmp4, Bmpr2, and Id2 were consistently upregulated upon infection of mouse peritoneal macrophages with Mtb H37Ra as well as virulent Mtb H37Rv." (PMID 29449840, 2018). "Moreover, the absence of the IFNγR rescued infection-driven BMP alterations: we found no loss of Bmp2 or Id1 expression, but reduced Grem2 expression in infected IFNγR KO mice compared to WT littermates." (PMID 35332152, 2022). "Thus, the downregulation of Bmp2 in response to infection depends on a functional T4SS." (PMID 35332152, 2022). "Since BMP2 can modulate and be modulated by the immune system and control intestinal homeostasis, the aim of this study was to correlate the production of intestinal BMP2 with cytokines and histopathological changes in mice infected with T. cruzi in different phases of experimental infection." (PMID 33561140, 2021). "In an infected rat femoral segmental defect, the dual-delivery composite resulted in substantially more new bone formation and a modest improvement in infection than PUR + BMP2 and collagen + BMP2 treatments." (PMID 26950123, 2016). "Ad-Cre infection in primary osteoblasts isolated from the β-cateninfx/fx mice inhibited Osthole-induced expression of Runx2, ALP, and BSP, as well as Bmp2." (PMID 20200936, 2010). "Consistent with previous findings, cultures infected with these doses of Ad.BMP-2 and Ad.BMP-4 generated approximately 30 to 60 ng/mL of gene product per 24 hours at day 3 post-infection." (PMID 19799789, 2009). "And deletion of the β-catenin expression by the infection of Ad-Cre into β-cateninflox/flox osteoblasts may inhibit osthole-stimulated expression of Runx-2, ALP, BSP, and BMP-2, suggesting that BMP-2 acts as the downstream factor of the β-catenin signaling." (PMID 37680712, 2023).
infection (continued). "Although BMP@Gel had an enhanced osteogenesis effect with BMP-2, it lacked anti-infection factors, and bone regeneration was unsatisfactory and limited by local and systemic infection status." (PMID 37103316, 2023). "Therefore, we next assessed the gene expression of two key BMPs (BMP2 and BMP6) at different time points after infection." (PMID 36713156, 2022). "Despite these matrix-dependent effects, the mRNA levels of Opg, Bmp2, and Spp1 did not change significantly during the infection, consistent with the reported antiosteogenic effects of inflammation and infection." (PMID 34357987, 2021). "Next, CNE-2 and CNE-1 cells were infected with lentivirus expressing oe-BMP2 to overexpress BMP2 and RT-qPCR and Western blot analysis were used to determine the expression of SMAD5-AS1 and miR-195 and mRNA and protein expression of BMP2 and SMAD5 following infection." (PMID 31921616, 2019). "The experimental groups included lysostaphin-delivering hydrogels with and without UAMS-1 infection containing 100 ng of BMP-2." (PMID 31114804, 2019). "In order to analyze the impact of HIF1αmu on BMP2 expression, we measured the ALP from BMSCs that were infected with HIF1αmu plus BMP2, the BMSCs that were infected with only BMP2, and the BMSCs without infection at 3, 6, 9, and 12 days after infection." (PMID 26018771, 2015). "There was no increase of SA-βgal(+) cells when Mock cells or MEF cells without infection were exposed to rBMP2 at 200 ng/mL, indicating that increase of BMP2 alone is not enough to induce cellular senescence." (PMID 22072987, 2011). "In addition, expression levels of BMP2 and OSF2, involved in osteoblasts recruitment and adhesion, were reduced by TGF-β1 treatment and Ad5-caAlk5 infection." (PMID 21124921, 2010). "In the absence of infection, MMs secrete BMP2 in a microbial-dependent manner to regulate neuronal activity and intestinal motility, and the expression of myeloid macrophage protective gene profile is enhanced after infection." (PMID 37138874, 2023). "After retrieving this patient's medical records (NO.114), 1 g BMP-2@CPC was applied to the patient, and there was no infection at the incision site." (PMID 39472366, 2024).
bone cyst (11 papers, 2017 to 2025). "However, there are also reports that high concentrations of BMP2 are associated with adverse effects, such as bone cysts and lipogenesis." (PMID 40358181, 2025). "Polymorphisms in BMP2 and BMP4 genes, such as rs235756 (BMP2) and rs17563 (BMP4), have been associated with cardiovascular and skeletal diseases." (PMID 39997941, 2025). "Bone cyst formation with BMP-2 can be attributed to the treatment’s pro-adipogenic effects, which reduce the overall bone quality." (PMID 37373757, 2023). "We also showed that there was a difference in BMP2 response between cell populations between the two skeletal diseases." (PMID 31771161, 2019). "Looking forward, we find a lack of information and understanding of the signals mediating normal BMP2 expression in the periosteal niche, both as a function of age and in the context of skeletal disease." (PMID 30735122, 2019). "Adverse effects of rhBMP-2 use may be explained at the cellular level, where BMP-2 has been shown to induce inflammatory cytokines, activate osteoclasts, and induce adipogenesis and bone cyst formation." (PMID 35463995, 2021).
cardiovascular disease (8 papers, 2017 to 2026). "The intricate crosstalk among the Notch signaling pathway, BMP2 and RUNX2 playsa pivotal role in the pathogenesis of cardiac fibrosis, influencing theprogression and outcomes of cardiovascular diseases." (PMID 39484128, 2024).
adenocarcinoma (5 papers, 2010 to 2023). A common cancer characterized by the presence of malignant glandular cells. "Although there have been previous reports of BMP2 expression in salivary glands in adenocarcinoma cell lines and mixed tumors, this is the first study to report that BMP2 expression is induced by duct ligation." (PMID 37033127, 2023). "In immortalized human bronchial epithelial cells and A549 adenocarcinoma cell lines, mycoplasma influences malignant transformation by activating the expression of the bone morphogenetic protein 2 (BMP2) growth factor." (PMID 35804901, 2022). "In such adenocarcinomas, a striking upregulation of BMP2 mRNA correlated with a short gene set (63 genes) whose expression was upregulated when LKB1 was mutated and underexpressed." (PMID 26701726, 2016). "A separate study also suggests that BMP2 may be involved after determining that BMP2 can induce microcalcification in adenocarcinoma cells while at the same time sparing normal tissues, possible through the formation of osteoblast-like cells being derived from pericytes." (PMID 26185749, 2015).
bacterial infection (3 papers, 2021 to 2025). "Meanwhile, BMP-2 served as both a target and a mediator of the inflammatory microenvironment: persistent bacterial infection and inflammatory responses could lead to the upregulation of BMP-2 expression by pro-inflammatory cytokines such as TNF-α." (PMID 41573683, 2025). "Therefore, this study demonstrated the efficacy of hBD3 in preventing bacterial infections during bone healing without affecting the activity of BMP2." (PMID 33557881, 2021).
benign tumors (3 papers, 2022 to 2024). "NSCLC exhibits significant overexpression of BMP2 compared to normal lung tissue and benign tumors, and depletion of BMP2 or its receptor BMPR2 has been shown to reduce cell migration and invasiveness." (PMID 38049682, 2023). "Although there is little to no BMP2 expression in normal lung tissue or benign tumors, BMP2 is highly expressed in 98% of non-small lung carcinoma (NSLC)." (PMID 35641992, 2022).
inflammation (3 papers, 2017 to 2025). Aberrant reaction of the microcirculation characterized by movement of fluid and leukocytes from the blood into extravascular tissues. "Taken together, these data reveal that both BMP9 and BMP10 synergize with TNFα to up-regulate endothelial-expressed molecules involved in leukocyte recruitment, in addition to BMP2, a factor previously implicated in endothelial inflammation." (PMID 28646109, 2017). "Like TGF-β, BMP-2 drives extracellular matrix expression and can promote fibrosis in chronic tendon inflammation, although it also promotes tenocyte migration." (PMID 36114555, 2022).